TEX53 (testis expressed 53)
Gene: Protein-coding gene on chromosome 9 (114,656,304 to 114,662,374, reverse strand). Ensembl gene ENSG00000230054.
Homologues: Orthologues: chimpanzee TEX53 (99% identical), macaque TEX53 (89% identical).